BMI1 (BMI1 proto-oncogene, polycomb ring finger)
Diseases named in the same sentence as BMI1 in open-access papers (continued):
Sharing a sentence is not in itself a finding about the gene and the disease.
cancer (continued). "Here, the current study evidenced that miR-381 could serve as a cancer suppressor in BCa with the involvement of BMI1 downregulation and the following Rho/ROCK inactivation." (PMID 33407350, 2021). "Bmi1 has been well studied in regard to these cellular mechanisms, specifically in cancer cells." (PMID 34360579, 2021). "Furthermore, it has been shown that elevated BMI-1 mRNA level contributes to anti-cancer drugs resistance." (PMID 34551814, 2021). "Previous studies have reported that various BMI-1 inhibitors induce cancer cell death." (PMID 34576269, 2021). "BMI1 is a key protein of polycomb repressive complex 1 that functions in integrity maintenance, and it has been increasingly known as a factor in the development of multiple human cancers." (PMID 33407350, 2021). "Bmi-1 is a member of the polycomb repressor complex 1 that mediates gene silencing by regulating chromatin structure and is indispensable for self-renewal of both normal and cancer stem cells." (PMID 34712655, 2021). "The observed CtBP2-mediated upregulation of BMI1 in the radioresistant CtBP2 overexpression organoids, could play a role in resistance of cancer cells with elevated CtBP2 to therapeutic chemo-radiation." (PMID 33972635, 2021). "B-lymphoma Moloney murine leukemia virus insertion region-1 (BMI1), a polycomb group family member, is an essential transcriptional repressor and plays an important role in the regulation of stem cell self-renewal in both endogenous and cancer stem cells." (PMID 34442383, 2021). "In addition, the knockdown of LAT1 in A400 and H1299 cells downregulated several cancer stemness genes including BMI1, Sox2, and Oct4." (PMID 34681614, 2021). "Very recently, we showed that the inhibition of BMI1 proteins not only helped to eliminate cancer stem cells, but also activated tumor‐intrinsic immune responses by stimulating STING‐IRF3 signaling.[6b] MOC1 cells were derived from 4NQO‐induced HNSCC through multiple passaging in vitro." (PMID 34258151, 2021). "Furthermore, the targeting of BMI1 or KLF4 has been demonstrated to benefit cancer patients or inhibit tumor progression in preclinical studies." (PMID 33828977, 2021). "Hedgehog has been previously reported to modulate BMI1 expression in normal and cancer contexts." (PMID 33993198, 2021). "While, BMI1 serves as an oncogene and targeting BMI1 suppresses cancer growth and prevents relapse." (PMID 34211849, 2021). "As shown, the targeting of BMI1 via several different mechanisms may provide therapeutic strategies for cancers that overexpress BMI1." (PMID 33804165, 2021). "Moreover, Orai1 is capable of endowing non-tumorigenic immortalized oral epithelial cells with self-renovation, and concurrently enhances transcribing pluripotent and cancer stem cells-associated agents such as Nanog, Sox2, KLF4, Oct4, Zeb1, Bmi1, and Zeb2." (PMID 32280305, 2020). "These miRNAs function in OSCC mainly through modulating the expression of proteins related to cancer stem cells (augmentation of CD44, c-Myc, and Oct-4), drug resistance (upregulation of P-gp and MRP1), and EMT (increase in BMI1 and MMP9 expression and loss of E-cadherin)." (PMID 32547936, 2020). "Bmi-1 levels were significantly higher in cancer than in normal endometrial tissue." (PMID 32059385, 2020). "Therefore, miR-203 and Bmi-1 appear to play important roles in the generation of cancer stem-like cells in OSCC." (PMID 33665161, 2020). "In conclusion, our results investigating the effects of PTC-318 on cancer cell lines indicate that inhibition of the oncogene BMI1 induces cancer cell death, making it a potential approach to treat certain types of cancers–either as a single agent or in combination with other inhibitors." (PMID 32343689, 2020). "Because of this, BMI1 is an attractive target for future clinical therapies of different cancers." (PMID 32343689, 2020).
cancer (continued). "In line with this, previous studies analyzed the correlation between SOX9, BMI1 and p21CIP in different types of cancers and showed independently that SOX9 regulates proliferation through a positive correlation with BMI1 and an inverse correlation with p21CIP expression." (PMID 31941916, 2020). "The current study brings new insights to BMI1 inhibition-induced mitotic lethality in cancer cells and presents a previously unknown role of NUMA1 in this process." (PMID 32343689, 2020). "In summary, our results for the first time showed that down‐regulation of BMI‐1 in cancer cells might affect expression of PHLPP1 and PHLPP2." (PMID 31863623, 2020). "The inhibition of the NEAT1 expression through the CRISPR-Cas9 method increased the sensitivity of radioresistant MDA-MB-231 cells to radiation and decreased their proliferation, the activity of cancer stem cells, and the expression of stemness genes, including BMI1, Oct4, and Sox2." (PMID 32922184, 2020). "It has been reported B-cell-specific Moloney leukemia virus insertion site 1 (Bmi-1) was correlated with poor overall survival in various cancer and involved in tumor initiation, progression and radiosensitivity through mediated transcription of p16Ink4a and p14ARF." (PMID 32182776, 2020). "BMI1 is a stem cell factor that is highly expressed in various human cancers, including AML." (PMID 32436945, 2020). "Studies have demonstrated that BMI1 can regulate cancer initiation and cell transformation." (PMID 33302959, 2020). "Except CD44+CD133+ subset and OV6+ subset, we found that HBx upregulated a subset with positive expression of ABCG2, a drug resistance-associated protein, which had been characterized by high expression of cancer stemness-related proteins, including Oct4, Bmi-1, and CD44." (PMID 32168902, 2020). "Thus, Timo AIII inhibited cancer stem cell phenotype, including cell migration and invasion, and subsequently suppressed cancer metastasis by targeting MMPs, BMI1, and cancer inflammatory infiltration." (PMID 32581782, 2020). "The `features associated with NUMA1, as well as its tumor-suppressing and cell-differentiating properties, suggested it as an attractive BMI1-antagonizing candidate, especially considering the role of BMI1 in maintaining cell stemness in healthy and cancer cells." (PMID 32343689, 2020). "Moreover, the expression of BMI‐1 was lower in tumours that exhibited the ability to metastasize to regional lymph nodes compared to non‐metastatic cancers." (PMID 31863623, 2020). "Similarly, to the protein expression results, there was a significantly lower BMI1 mRNA expression in cancers that exhibited the ability to metastasize to regional lymph nodes compared to non‐metastatic cancers." (PMID 31863623, 2020). "TWIST is associated with different signaling cascades, like TGFβ and v-akt oncogene homolog (AKT)/phosphoinositide 3-kinase (PI3K), to promote cancer cell invasion and metastasis with the help of B lymphoma Mo-MLV insertion region 1 homolog (BMI1) and v-akt oncogene homolog 2 (AKT2)." (PMID 32397221, 2020). "Overexpression of BMI1 is also found in cancer cells with resistance to chemotherapy agents." (PMID 32726929, 2020). "Moreover, BMI-1 overexpression in cancer cells has been reported to activate PI3K/AKT signaling pathway, and induce cell migration and metastasis." (PMID 32348447, 2020). "BMI1, which is a major component of the polycomb group complex 1, is an essential epigenetic repressor of multiple regulatory genes and has been identified as a cancer stem cell (CSC) marker in several cancers." (PMID 32524353, 2020). "Both Bmi-1 and Ki-67 were more strongly expressed in carcinoma than in normal endometrial tissues." (PMID 32059385, 2020). "In addition, the level of BMI1 mRNA was drastically decreased in the carcinoma tissues, and its elevated expression was involved in human colorectal carcinogenesis via inhibiting the INK4a/ARF proteins." (PMID 32099526, 2020).
cancer (continued). "The expression of both Bmi-1 and Ki-67 was higher in carcinoma than in normal endometrial tissue." (PMID 32059385, 2020). "Twist and Bmi1 are also both involved in the proliferation and tumourigenesis of cancers." (PMID 30353649, 2019). "Furthermore, simultaneous expressions of YB-1 and the other four (SOX2, POU3F2, OCT-4, and OLIG1) or five (SOX2, SALL2, OCT-4, POU3F2, and Bmi-1) transcription factors in YB-1 knockout cancer stem cells restored the stemness of YB-1 knockout cancer stem cells." (PMID 31375149, 2019). "Moreover, cholesterol treatment inverted metformin-repressed expressions of several cancer-associated genes (e.g., Bcl-xL BCL2, Zeb1, vimentin, BMI1)." (PMID 30625181, 2019). "This phenomenon consisted of the report that Bmi1 gene was up-regulated in cancer cells and tissue." (PMID 31366257, 2019). "Many studies have proved that BMI1, a stem cell factor, is upregulated in various cancer cells." (PMID 30871059, 2019). "Several recent studies on cancer stem cells have shown that down-regulation of Bmi1 could inhibit the tumor cell growth in different types of cancer, indicating that Bmi1 can be a potential target for tumor treatment." (PMID 31366257, 2019). "Gemcitabine could promote the binding of phosphorylated STAT3 to the Bmi1 promoter, which further enhances the stemness and migration of cancer cells." (PMID 31244991, 2019). "Overexpression of Bmi1 gene is an important feature of cancer stem cell in various human tumors." (PMID 31366257, 2019). "Strong evidences have proved that the key self-renewal regulator BMI-1 could be a central target for cancer therapy." (PMID 31640758, 2019). "Consequently, cancer cells expressing ROR1 at higher levels had increased BMI-1 expression and stemness properties, as demonstrated by elevated Nanog, Oct3/4 and Sox2 expression." (PMID 31382410, 2019). "Furthermore, there is evidence that targeting cellular plasticity can be effective – a study targeting BMI-1-expressing cells showed that this reduced the number of cancer-initiating cells in vivo." (PMID 30792270, 2019). "Therefore, Bmi1 gene can be a potential target for small interfering RNA (siRNA) mediated cancer therapy." (PMID 31366257, 2019). "In particular, BMI1 might be required for the maintenance and renewal of cancer initiating stem cells and might be involved in the growth of GBMs." (PMID 30658672, 2019). "The Wnt5a-ROR1-dependent upregulation of YAP/TAZ and BMI-1 points toward a new positive feedback loop that may play an important role in mediating cancer stemness, tumorigenesis and drug resistance." (PMID 31382410, 2019). "BMI1 is required for the maintenance of hematopoietic stem cells, neural stem cells, and intestinal stem cells; BMI1 is also important in sustaining CSCs for multiple cancer types." (PMID 30934773, 2019). "However, few studies correlated Bmi1 with cancer immune escape, rendering the exploration of Bmi1 in cancer immunity a necessity." (PMID 31088566, 2019). "As a tumor cell self-renewal inhibitor, Bmi1 siRNA could prevent the tumor relapse by inhibiting cancer stem cells." (PMID 31366257, 2019). "Finally, we achieved the only compound QW24 that dramatically suppressed cancer cells proliferation and down-regulated BMI-1 simultaneously." (PMID 31640758, 2019). "Collectively, these findings suggest that re-activation of key tumor suppressor genes following RING1A/RING1B/BMI1 inhibition may be a therapeutic strategy to inhibit cancer stem-cell proliferation and/or induce cell death." (PMID 30781493, 2019). "The role of the polycomb E3 ubiquitin ligase subunit RING1A/RING1B/BMI1 and H2AK119ub1 in the maintenance of stem-cell populations in adult tissues suggests it may harbor a role in the maintenance of cancer stem cells." (PMID 30781493, 2019). "Moreover, β-Asarone also suppressed the expression of cancer stem cell-related proteins (c-Myc and Bmi1) in a dose-dependent manner." (PMID 31171917, 2019).
cancer (continued). "Overall, these results indicate that Bmi1 as a regulating gene for cancer stem cell is an effective target for cancer treatment using siRNA and co-delivery of UA and Bmi1 siRNA using folate-targeted liposomes is a promising strategy for improved anti-tumor effect." (PMID 31366257, 2019). "BMI1 is up-regulated in cancer and promotes stem cell self-renewal." (PMID 29401683, 2018). "BMI1, encoding for PCGF4, is the best studied PRC1 gene in cancer to date." (PMID 30139998, 2018). "As a core member of Polycomb group proteins (PcG), B-cell-specific Moloney murine leukemia virus integration site 1 (BMI1) plays an important role in epigenetics, participates in important cellular events and is identified as aberrantly expressed in various human cancers." (PMID 29685168, 2018). "BMI1 expression is controlled by different miRNAs in cancer." (PMID 29401683, 2018). "Moreover, the expression of β-catenin and the relevant target for cancer therapeutics, Bmi1, were found decreased in tumors after c-PTIO treatment." (PMID 29329541, 2018). "miR-200c suppresses cell growth and metastasis through Bmi-1 down-regulation in cancer cells." (PMID 29765508, 2018). "The functional fate of phosphorylated BMI1 thus remains context and cancer specific." (PMID 28270146, 2017). "Hence, our study not only provides better understanding of let‐7i's tumor suppressing roles and the underlying mechanisms but also substantiates the importance of targeting BMI1 and let‐7i for treating cancers." (PMID 28079973, 2017). "Clearly, it appears that BMI1 is differently dysregulated in different types of cancer." (PMID 28445986, 2017). "In addition, our findings suggest that ERK3 kinase is a potential new therapeutic target of cancers, particularly those with BMI1 overexpression." (PMID 28079973, 2017). "BMI-1 was shown to confer radioresistance to normal and cancerous neural stem cells through recruitment of the DNA double-strand break response machinery, and its downregulation sensitized cancer cells to ionizing radiation." (PMID 28968963, 2017). "This positive correlation between gankyrin and Lgr5 or Bmi1 suggests that gankyrin might be related with cancer stem cell behavior in IBD patients." (PMID 28160571, 2017). "The BMI1 over-expression resulting from this cascade was demonstrated to increase the ability of the cells to form mammospheres in culture, a manifestation of a cancer stem cell phenotype that was antagonized by DKK1 inhibitor expression, in this cell model." (PMID 28587163, 2017). "Importantly, such resistance to inflammation-associated colon tumorigenesis in Mx1-Cre;Gankyrinf/f mice was associated with a significant reduction of pro-inflammatory responses (IL-17 and TNF-α) and expression of cancer stem cell markers (Bmi1 and Sox9)." (PMID 28160571, 2017). "In addition, NG type cells had a significantly higher percentage of cancer stem cells that express CD133+ Sox2+ or AGR2+ BMI1+, and were more tolerant to treatment with the chemotherapeutic agents cisplatin and etoposide." (PMID 28736504, 2017). "BMI1 is required for the maintenance of adult stem cells, and is involved in carcinogenesis of different cancers, and may be a marker for cancer stem cells in HNSCC." (PMID 28704968, 2017). "Indeed, CD44 and the B-cell-specific Moloney murine leukemia virus insertion site 1 (BMI1) support the stem cell state in both cancer cells and embryonic stem cells." (PMID 29123181, 2017). "Bmi1 is implicated in CSC self-renewal through regulation of genes important for cell cycle control and stem cell fate decisions, as well as regulation of survival genes and inhibition of cellular senescence in multiple cancer models." (PMID 28418883, 2017). "Enforced overexpression of Bmi1 facilitated malignant transformation, cancer cell proliferation, EMT and metastatic spreading, whereas its depletion inhibited cell proliferation, migration and invasion and induced cell apoptosis and senescence both in vitro and in vivo." (PMID 29200967, 2017).
cancer (continued). "BMI-1 was shown to maintain normal and cancer stem cells self-renewal phenotype." (PMID 28968963, 2017). "Indeed, genetic silencing and pharmacological inhibition of Bmi1 induced apoptosis and senescence, enhanced chemosensitivity, and diminished invasive and metastatic potentials, thus ultimately compromised cancer progression." (PMID 29200967, 2017). "Indeed, we observed that PEITC treatment was unable to increase expression of pro-apoptotic genes in HCT116-BMI-1 cells, indicating that BMI-1 overexpression increases cancer cell survival by blocking the effects of PEITC." (PMID 28079155, 2017). "The role of Bmi1 in the miR-218-mediated inhibition of cancer stemness was further clarified." (PMID 27926533, 2017). "Silencing of BMI1 sensitizes the human cancers to chemotherapeutic drug." (PMID 28655885, 2017). "Moreover, miR-128 can inhibit BMI-1, cancer stem cell proliferation, and xenograft growth in vitro and in vivo." (PMID 29299167, 2017). "Notably, BMI-1 has been shown to mediate the growth and survival of cancer stem cells in solid and hematological malignancies." (PMID 29262596, 2017). "In cancer cells with BMI1 upregulation, the elevated levels of BMI1 potentially may compromise DDR, thereby contributing to genome instability, a hallmark of tumorigenesis." (PMID 29163782, 2017). "ERK3 then acts as an important downstream mediator of BMI1 in promoting cancer cell migration." (PMID 28079973, 2017). "Our study identified ERK3 as a new target of BMI1 that is critical for cancer cell motility." (PMID 28079973, 2017). "As BMI-1 has been assigned an important role in conferring stemness to tumor cells in various types of cancer, we suggest that targeting BMI-1 in relapsed cancer patients including MM could represent a potential therapeutic strategy." (PMID 29262596, 2017). "Bmi-1 is one of the polycomb group of genes, which functions as an oncogene in many cancers." (PMID 27009837, 2016). "We hypothesized that PTC-209 downregulation of BMI1 may upregulate miR-200c/141 cluster, which could further downregulate BMI1 and oncogenic phenotypes of the cancer cells." (PMID 27105531, 2016). "More importantly, knockdown of endogenous Ang-1 resulted in suppression of both CSC (CD49f an Bmi-1) and quiescence (p27) markers in PC-3, supporting the hypothesis that Ang-1 produced by cancer cells is crucial for CSC maintenance." (PMID 25978029, 2016). "Although the tracing period was limited to 4 weeks owing to mouse death, the results indicate that at least some Bmi1-positive cells could serve as cancer stem cells, aiding the long-term maintenance of developing tumors." (PMID 28004815, 2016). "Importantly, BMI1 is frequently upregulated and its expression correlates with poor prognosis and therapy failure in several types of cancer including OvCa Experimental reduction of BMI1 increases susceptibility to cytotoxic agents and radiation therapy." (PMID 26918603, 2016). "We speculate that this autoregulatory loop maintains a basal endogenous level expression of BMI1 and miR-200c/141 necessary for the proper physiology of an organism, and that its deregulation can result in pathological conditions such as cancer and ageing." (PMID 27105531, 2016). "Here, in this study we constructed an AAV vector (Ad-Bmi-1i) containing Bmi-1 shRNA driven by its own promoter, which could specifically express and function in cancer cells with higher Bmi-1 expression." (PMID 27009837, 2016). "Studies showed that BMI-1 could promote self-renew, differentiation and tumor formation of CSCs and invasion/metastasis of human cancer." (PMID 26840020, 2016). "In addition, the expression of BMI-1, a biomarker of cancer stem cells, was remarkably repressed in USP22 knockdown cells." (PMID 27145278, 2016). "Moreover, BMI-1 was shown to mediate the growth and survival of cancer stem cells in several solid and haematological malignancies." (PMID 26935956, 2016).